DMRTA1 (DMRT like family A1)
Synonyms: DMO; DMRT4
Tractability: No criterion of Open Targets' tractability assessment is met for any kind of drug.
Gene: Protein-coding gene on chromosome 9 (22,446,824 to 22,455,740, forward strand). Ensembl gene ENSG00000176399.
Subcellular location: Nucleus
Subcellular location (Human Protein Atlas): Vesicles
Gene Ontology:
Molecular function: protein binding; sequence-specific double-stranded DNA binding; DNA-binding transcription factor activity, RNA polymerase II-specific; RNA polymerase II cis-regulatory region sequence-specific DNA binding; double-stranded DNA binding; identical protein binding; sequence-specific DNA binding
Biological process: regulation of transcription by RNA polymerase II; sex differentiation; regulation of DNA-templated transcription
Cellular component: chromatin; nucleus
Genetic constraint (gnomAD): Loss-of-function variants: 35 observed, 36.28 expected, observed/expected ratio (o/e) 0.96, 90% interval 0.74 to 1.28. The synonymous counts are far from expectation, so gnomAD's model fits this gene poorly and the ratio says little. Missense variants: 824 observed, 621.91 expected, observed/expected ratio (o/e) 1.33, 90% interval 1.25 to 1.4. Synonymous variants: 344 observed, 264.64 expected, observed/expected ratio (o/e) 1.3, 90% interval 1.19 to 1.42.
Homologues: Orthologues: chimpanzee DMRTA1 (98% identical), macaque DMRTA1 (94% identical), pig DMRTA1 (79% identical), dog DMRTA1 (79% identical), rabbit DMRTA1 (77% identical), rat Dmrta1 (68% identical), guinea pig DMRTA1 (67% identical), mouse Dmrta1 (67% identical), tropical clawed frog dmrta1 (46% identical), Caenorhabditis elegans dmd-7 (14% identical), Caenorhabditis elegans dmd-9 (9% identical). Paralogues in human: DMRTA2 (38% identical), DMRT3 (26% identical), DMRT2 (22% identical), DMRT1 (18% identical), DMRTC2 (17% identical), DMRTB1 (16% identical), DMRTC1 (8% identical), DMRTC1B (8% identical).
Diseases named in the same sentence as DMRTA1 in open-access papers:
DMRTA1 is named in the same sentence as 7 diseases in open-access papers, as found by Europe PMC text mining. Sharing a sentence is not in itself a finding about the gene and the disease. The quoted sentences say what the papers report.
tumor (1 paper, 2023). "Overexpression of DMRTA1 also increased tumor growth and volume in cisplatin-treated nude mice." (PMID 37744275, 2023).
DMRTA1 also shares sentences with these, for which no sentence is quoted: astrocytomas (1 paper); cyst (1); glioma (1); mesothelioma (1); Ovarian cyst (1); pancreatic cancer (1).